TLR6 (toll like receptor 6)
Description:
Participates in the innate immune response to Gram-positive bacteria and fungi. Specifically recognizes diacylated and, to a lesser extent, triacylated lipopeptides. In response to diacylated lipopeptides, forms the activation cluster TLR2:TLR6:CD14:CD36, this cluster triggers signaling from the cell surface and subsequently is targeted to the Golgi in a lipid-raft dependent pathway. Acts via MYD88 and TRAF6, leading to NF-kappa-B activation, cytokine secretion and the inflammatory response. Recognizes mycoplasmal macrophage-activating lipopeptide-2kD (MALP-2), soluble tuberculosis factor (STF), phenol-soluble modulin (PSM) and B.burgdorferi outer surface protein A lipoprotein (OspA-L) cooperatively with TLR2. In complex with TLR4, promotes sterile inflammation in monocytes/macrophages in response to oxidized low-density lipoprotein (oxLDL) or amyloid-beta 42. In this context, the initial signal is provided by oxLDL- or amyloid-beta 42-binding to CD36. This event induces the formation of a heterodimer of TLR4 and TLR6, which is rapidly internalized and triggers inflammatory response, leading to the NF-kappa-B-dependent production of CXCL1, CXCL2 and CCL9 cytokines, via MYD88 signaling pathway, and CCL5 cytokine, via TICAM1 signaling pathway, as well as IL1B secretion.
Synonyms: CD286
Tractability: Antibody: UniProt places it where antibodies can reach, with high confidence; its Gene Ontology location is reachable by antibodies, with high confidence; UniProt predicts a signal peptide or a membrane-spanning region. PROTAC: ubiquitination databases record sites on it; a small molecule that binds it is known.
Target class: Toll-like and Il-1 receptors; Membrane receptor
Gene: Protein-coding gene on chromosome 4 (38,822,897 to 38,856,901, reverse strand). Ensembl gene ENSG00000174130.
Subcellular location: Cell membrane; Cytoplasmic vesicle, phagosome membrane; Membrane raft; Golgi apparatus
Subcellular location (Human Protein Atlas): Endoplasmic reticulum
Pathways (Reactome):
Immune System: ER-Phagosome pathway; MyD88:MAL(TIRAP) cascade initiated on plasma membrane; Regulation of TLR by endogenous ligand; Toll Like Receptor TLR6:TLR2 Cascade
Disease: IRAK4 deficiency (TLR2/4); MyD88 deficiency (TLR2/4); RSV-host interactions
Gene Ontology:
Molecular function: identical protein binding; lipopolysaccharide immune receptor activity; protein binding; protein heterodimerization activity; signaling receptor binding; Toll-like receptor 2 binding; transmembrane signaling receptor activity; amyloid-beta binding; lipopeptide binding; signaling receptor activity; diacyl lipopeptide binding
Biological process: antibacterial innate immune response; cellular response to amyloid-beta; cellular response to diacyl bacterial lipopeptide; cellular response to oxidised low-density lipoprotein particle stimulus; detection of diacyl bacterial lipopeptide; MyD88-dependent toll-like receptor signaling pathway; negative regulation of interleukin-8 production; negative regulation of toll-like receptor 2 signaling pathway; positive regulation of canonical NF-kappaB signal transduction; positive regulation of JUN kinase activity; toll-like receptor TLR6:TLR2 signaling pathway; activation of NF-kappaB-inducing kinase activity; defense response to bacterium; immune response; inflammatory response; innate immune response; positive regulation of cytokine production involved in inflammatory response; positive regulation of extrinsic apoptotic signaling pathway; positive regulation of gene expression; positive regulation of interleukin-1 beta production; positive regulation of interleukin-6 production; positive regulation of macrophage activation; positive regulation of nitric oxide biosynthetic process; positive regulation of NLRP3 inflammasome complex assembly; positive regulation of reactive oxygen species biosynthetic process; and 9 more
Cellular component: Golgi apparatus; membrane raft; plasma membrane; receptor complex; Toll-like receptor 2-Toll-like receptor 6 protein complex; membrane; phagocytic vesicle membrane
Genetic constraint (gnomAD): Loss-of-function variants: 17 observed, 25.89 expected, observed/expected ratio (o/e) 0.66, 90% interval 0.45 to 0.99. The upper end of that interval is the gene's LOEUF score, 0.99, which puts it in group 4 of 6, group 1 being the genes least tolerant of losing a copy. Missense variants: 786 observed, 961 expected, observed/expected ratio (o/e) 0.82, 90% interval 0.77 to 0.87. Synonymous variants: 340 observed, 353.73 expected, observed/expected ratio (o/e) 0.96, 90% interval 0.88 to 1.05.
Homologues: Orthologues: macaque TLR6 (96% identical), pig TLR6 (79% identical), rabbit TLR6 (79% identical), guinea pig TLR6 (74% identical), mouse Tlr6 (74% identical), rat Tlr6 (72% identical), tropical clawed frog tlr6 (44% identical), tropical clawed frog XB5889249 (42% identical), tropical clawed frog tlr1 (41% identical), zebrafish tlr1 (34% identical). Paralogues in human: TLR1 (68% identical), TLR10 (48% identical), TLR2 (29% identical), TLR3 (22% identical), TLR8 (21% identical), TLR4 (19% identical), TLR7 (19% identical), TLR5 (19% identical), CD180 (15% identical), LRRC32 (15% identical), NRROS (14% identical), RXFP2 (14% identical), and 10 more.
Diseases named in the same sentence as TLR6 in open-access papers:
TLR6 is named in the same sentence as 145 diseases in open-access papers, as found by Europe PMC text mining. Sharing a sentence is not in itself a finding about the gene and the disease. The quoted sentences say what the papers report.
asthma (22 papers, 2005 to 2025). "The polymorphism of TLR6 rs5743810 has some exploratory correlation with airway reactivity and a weak correlation with childhood asthma." (PMID 40672946, 2025). "In children exposed to a farm environment, those carrying the TLR6 rs1039559 T-allele and the TLR6 rs5743810 C-allele have a lower risk of early-onset asthma compared with healthy children." (PMID 40672946, 2025). "Clinical experiments demonstrated that Ser249Pro polymorphism in TLR6 has a protective effect on asthma." (PMID 33066754, 2020). "For those with childhood farm exposure, carriers of the TLR6-rs1039559 T-allele (p-interaction = 0.009) and TLR6-rs5743810 C-allele (p-interaction = 0.02) were associated with lower risk of early-onset asthma." (PMID 28262750, 2017). "Being exposed to a farm environment in childhood was protective against early-onset asthma for those with TLR6-rs1039559 T-allele and TLR6-rs5743810 C-allele, showing a clear difference in the pattern of interaction for early- and late-onset asthma." (PMID 28262750, 2017). "We have previously studied the TLR1 rs5743618, TLR2 rs5743708, and TLR6 rs5743810 polymorphisms and reported their associations with post-bronchiolitis asthma at preschool age10." (PMID 28592890, 2017). "For those with childhood farm exposure, the TLR6-rs1039559 T-allele was associated with a markedly reduced risk of early-onset asthma (additive genetic model for the T-allele OR = 0.34, 95%CI 0.16–0.73), but not for those without childhood farm exposure." (PMID 28262750, 2017). "In conclusion, we have shown for the first time that farming exposure in early-life modified the relationship between polymorphisms in the TLR6 gene and asthma that started in early life." (PMID 28262750, 2017). "Again in those with childhood farm exposure having the TLR6-rs5743810 C-allele was associated with a lower risk of early-onset asthma (additive genetic model for the C-allele OR = 0.41, 95%CI 0.19–0.86)." (PMID 28262750, 2017). "Furthermore, a polymorphism in the TLR6 gene contributed to the development of asthma and allergic rhinitis, whereas an SNP in the TLR10 gene was negatively associated with asthma development." (PMID 37759430, 2023). "Furthermore, genetic variants in TLR6 exerting their protection on asthma were linked with greater mononuclear cell generation of Th1-type cytokines." (PMID 33066754, 2020). "Using a longitudinal cohort that has been followed from childhood (age 7 years) into adult-life (age 45 years when this clinical study was conducted), we identified an effect modification by farm exposure in childhood on the association between TLR6 SNPs and asthma phenotypes based on age of onset." (PMID 28262750, 2017). "It is positioned in TLR6 gene, that has been associated with asthma and coronary artery disease." (PMID 26442097, 2015). "Allele frequencies of the TLR6 Ser249Pro polymorphism in asthma children vs. controls." (PMID 16188043, 2005). "This indicates that TLR6 may play a certain protective or regulatory role in asthma through the IL-23/IL-17 pathway, and its low expression may be associated with the aggravation of asthma." (PMID 40672946, 2025). "In contrast to our finding of a lower risk of asthma in individuals with the TLR6-rs1039559 T-allele and early farm exposure, their study found higher IgE levels at age two years in individuals with the TLR6-rs1039559 CC-genotype and exposure to two or more older siblings." (PMID 28262750, 2017). "In the development of asthma, TLR6 not only regulates the immune response through signaling pathways, but its genetic polymorphisms also jointly influence the susceptibility to the disease along with environmental exposure." (PMID 40672946, 2025). "Exogenous IL-23 treatment restored the production of IL-17A in asthma TLR6-/- mice, significantly reducing airway hyperresponsiveness, inflammation and pulmonary fungal burden." (PMID 40672946, 2025).
asthma (continued). "In the asthma model of TLR6-/- mice induced by fungal or house dust mite antigens, airway hyperresponsiveness, inflammation and remodeling worsened significantly, but the levels of IL-23 and IL-17 in the whole lung decreased significantly." (PMID 40672946, 2025). "In conclusion, the TLR2/TLR6 agonist FSL-1 administered in the lungs by nasal instillation after the establishment of experimental asthma significantly decreased AHR and eosinophilia." (PMID 39273551, 2024). "Single nucleotide polymorphisms (SNP) in five different TLRs (TLR2, TLR4, TLR6, TLR9, TLR10) were described to significantly contribute to asthma susceptibility, severity, and responsiveness." (PMID 37759430, 2023). "With the use of a series of bioinformatics analyses, we highlighted 11 important genes such as GNGT2, TLR6, and TTC19 as authentic risk genes associated with moderate-to-severe/severe asthma." (PMID 33066754, 2020). "Being exposed to a farm environment in childhood was protective against childhood-onset asthma for those with TLR2/-16934 T-allele, TLR6-rs1039559 T-allele and TLR6-rs5743810 C-allele." (PMID 31921716, 2019). "Specifically, we examined the interaction between TLR6 SNPs and childhood farm exposure for these early-onset asthma phenotypes and found comparable findings for both phenotypes." (PMID 28262750, 2017). "TLR1, TLR2, TLR6, and TLR10 comprise the TLR2 subfamily, and TLR1, TLR2, TLR6, and TLR10 gene polymorphisms seem to play a role in susceptibility to asthma, atopic eczema, and allergic rhinitis." (PMID 28592890, 2017). "There was strong evidence for interactions between the TLR6-rs1039559 and TLR6-rs5743810 SNPs and childhood farm exposure for early-onset asthma (p = 0.009 and p = 0.02 respectively)." (PMID 28262750, 2017). "The findings for the interaction between TLR6 and childhood farm exposure for asthma were strongly comparable to the findings with all participants included." (PMID 28262750, 2017). "Recent studies suggest a protective role of TLR6 activation in asthma via the regulation of cytokine expression by dendritic cells." (PMID 27101288, 2016). "Only two children (8%) with wild genotypes in the TLR1, TLR2 and TLR6 genes had asthma during the first six years of life, compared to 30% in those with variant genotypes." (PMID 26741133, 2016). "It has been shown that the T allele of the rs2381289 single nucleotide polymorphism (SNP) in TLR6 contributes to the development of allergic rhinitis and asthma, while the A allele of rs11466651 SNP in TLR10 is negatively associated with asthma development." (PMID 26617525, 2015). "Genetic variations in TLR1, TLR2, TLR4, TLR6 and TLR10 have been associated with the development of asthma." (PMID 24524443, 2014). "Haplotype spanning of polymorphisms in TLR6 and TLR10 (see TLR10) revealed an association with childhood asthma, indicating no individual but a combined influence of these polymorphisms on asthma in children." (PMID 23496969, 2013). "We evaluated here the role of a coding variation, Ser249Pro, in the TLR6 gene in the pathogenesis of asthma, atopic dermatitis (AD) and chronic obstructive pulmonary disease (COPD)." (PMID 16188043, 2005). "Notably, two TLR6 SNPs (rs1039559 and rs5743810) were found to protect against early-onset asthma in individuals with childhood exposure to a farming environment." (PMID 40761635, 2025). "In summary, current study provides several lines of evidence to support that 11 highlighted genes including GNGT2, TLR6, and TTC19 could be treated as genuine moderate-to-severe/severe asthma-associated genes." (PMID 33066754, 2020). "Therefore, we investigated the effect of a preventative treatment with combinations of Tlr1, Tlr2 and Tlr6 mRNA in a House Dust Mite-induced mouse model of asthma." (PMID 27101288, 2016).
asthma (continued). "Furthermore, we found that the expression of some molecules such as CD14, TLR5, TLR6, TLR8, TREM-1, but also IRAK-1 and IRAK-2 genes was significantly negatively associated with total serum IgE, atopic sensitization, or asthma." (PMID 24603716, 2014). "TLR2, TLR6, TLR9, and TLR10 have been associated with asthma in several studies." (PMID 23496969, 2013). "For TLR6, rs6531666, rs5743789, rs5743798, and rs5743810 significant associations with asthma and atopic asthma were found, but not with asthma in other studies." (PMID 23496969, 2013). "We further speculated that TLR6 coding variation might also play a role in the pathogenesis of COPD since it is – like asthma – a common chronic lung disease characterized by chronic airway inflammation and airway hyper-responsiveness." (PMID 16188043, 2005). "Variation in TLR6 might play a role in the pathogenesis of childhood asthma." (PMID 16188043, 2005). "Meanwhile, in an independent dataset of GSE123750, we found that TTC19 (P = 0.0078), TLR6 (P = 0.0086), and GNG12 (P = 0.045) were significantly expressed in severe asthma by comparison with mild-moderate asthma." (PMID 33066754, 2020). "There were 8 of 11 genes (8/11 = 72.7%) showing significantly different expression profiles between severe asthma and controls; for example, GNGT2, TLR6, TTC19, LNPEP, SLC22A5 and HLA-DQA1." (PMID 33066754, 2020). "Here, based on the data of asthma-protecting TLR-haplotypes, we investigated the intratracheal application of combinations of chemically modified Tlr1, Tlr2 and Tlr6 mRNA in a House Dust Mite (HDM)-induced mouse model of asthma." (PMID 27101288, 2016). "In this work it was observed that in the absence of TLR6, there was a lower production of IL-23 and Th17 response, which resulted in exacerbated asthma response." (PMID 23984400, 2013). "Puthothu and Heinzmann, who involved 322 asthmatic children and 270 randomly selected controls to assess whether TLR6, TLR10, or both were involved in asthma genetics, found no individual association between TLR10 (rs11096956) and bronchial asthma." (PMID 40218167, 2025). "Finally, Tlr6−/− mice treated with Aspergillus fumigatus and house dust mite (HDM) antigen exhibited increased airway hyper-responsiveness, inflammation, and remodeling compared with WT asthmatic groups, suggesting that TLR6 may exert protective effects in asthma." (PMID 39273551, 2024).
tuberculosis (12 papers, 2007 to 2024). A chronic, recurrent infection caused by the bacterium Mycobacterium tuberculosis. "In a previous study, we found an association of the rs4986790 (TLR4) and rs5743810 (TLR6) polymorphisms with the risk of developing tuberculosis." (PMID 39339847, 2024). "SNPs in TLR2 and TLR6 were previously associated with leprosy or tuberculosis, but their specific roles are less understood." (PMID 35141236, 2021). "The SNP rs5743810 of TLR6 has been associated with susceptibility to tuberculosis among ethnic African, European or Hispanic groups." (PMID 35141236, 2021). "Our study revealed certain associations between TLR4 and TLR6 polymorphisms and HIV–tuberculosis coinfection." (PMID 37606452, 2023). "In individuals with tuberculosis, the G/A (TLR6-rs5743810) and G/T (TLR10-rs11096957) genotypes have a significant association with a higher susceptibility to developing pulmonary tuberculosis (OR = 2.48, 95% CI 1.62–3.85)." (PMID 37888601, 2023). "Genotypic frequency distributions were in accordance with the Hardy–Weinberg equilibrium in both HIV and HIV–tuberculosis samples for all loci except rs5743810 (TLR6) in HIV patients (p = 0.036)." (PMID 37606452, 2023). "At the same time, comprehensive analysis of SNP allele frequencies in HIV and HIV–tuberculosis samples has not previously been performed, in particular for TLR6 and TLR8 as the most promising markers of the genetic risk of coinfection." (PMID 37606452, 2023). "Compared to control subjects, African American tuberculosis cases had a significantly increased frequency of rare NSPs in TLR1 (OR = 3.32; P = 0.002), TLR6 (OR = 1.85; P = 0.040), and TLR10 (OR = 1.76; P = 0.009)." (PMID 18091991, 2007). "In support of this hypothesis, the TLRs are upregulated as a group in both melioidosis (TLR1, TLR2, TLR4, TLR5, TLR6, TLR8 and TLR10) and tuberculosis (TLR2, TLR4, TLR5, TLR6, TLR7, TLR8)." (PMID 23383015, 2013). "In a recent study, an increased expression of TLR-1, TLR-2, TLR-4 and TLR-6 has been reported at the mRNA level in peripheral blood mononuclear cells, but not in broncho-alveolar lavage cells from patients with tuberculosis compared to healthy controls." (PMID 20718957, 2010). "TLR polymorphism with a significant association with pulmonary tuberculosis was present in TLR1 rs5743572 in intron, TLR2 rs3804100 in exon, and TLR6 rs5743808 in exon and among MDR-TB isolates from patients with pulmonary MDR-TB of a severe and moderate/mild degree." (PMID 36611413, 2022). "In pulmonary leucocytes obtained from patients with tuberculosis, NOD2 mRNA expression correlated with TLR2 (p = 0.02) and TLR4 (p = 0.01) but not with TLR6 mRNA expression (p = 0.17)." (PMID 17705850, 2007).
COVID-19 (10 papers, 2021 to 2025). A disease caused by infection with severe acute respiratory syndrome coronavirus 2. "Our results suggest that the TLR1, TLR4, TLR6, and TLR10 variants may influence the outcome during corticoid treatment in COVID-19 patients." (PMID 40149530, 2025). "Also, higher levels of both TLR2 and TLR6 genes were observed with the severity of COVID-19." (PMID 35573725, 2022). "Severe COVID-19, however, is characterized by additional activation of TLR1, TLR2, TLR4, TLR5, TLR6, NOD1 and NOD2, which are primarily responsive to bacterial antigens." (PMID 36769320, 2023). "In the case of COVID-19, innate immunity detects SARS-CoV-2 through pattern-recognition receptors (TLR1, TLR4, and TLR6) and activates downstream cascades to initiate viral clearance." (PMID 36833234, 2023). "Therefore, the analysis of the genotypes of TLR2, TLR3, TLR4, TLR6, TLR7, TLR8, and TLR9 is important for the study of COVID-19." (PMID 35327350, 2022). "The results suggested that the upregulation of MMP9 and TLR6 by Spike were mainly occured in THP-1 cells, which consisted with our GO analysis that myeloid cells, which contain monocytic cells were activated in COVID-19 patients." (PMID 33679778, 2021). "By contrast, expression of TLR4, TLR5, TLR6, and TLR7 was not altered in COVID-19-derived monocytes." (PMID 37310504, 2023). "Consistent data indicate that TLR1, TLR5, TLR6, TLR8, NOD1, NOD2 and RIG1 are not activated in severe COVID-19." (PMID 33672738, 2021).